CD4 (CD4 molecule)
Diseases named in the same sentence as CD4 in open-access papers (continued):
Sharing a sentence is not in itself a finding about the gene and the disease.
laryngeal carcinoma (14 papers, 1996 to 2024). Carcinoma that arises from the laryngeal epithelium. "Of the 22 cell types explored, high infiltration of M1 macrophages, dendritic cells (DC), and CD4+ T cells were associated with a statistically significant prolongation of survival in laryngeal cancer." (PMID 37444620, 2023). "We also found that the PD-1 expression on CD4+ T cells from lymph node samples was associated with a 1.5-fold increased risk of death among patients diagnosed with laryngeal cancer." (PMID 35158748, 2022). "What is important, the level of PD-1 on CD4+ T cells in lymph nodes increased the risk of death, so it can be an important prognostic factor (marker) for laryngeal cancer patients’ treatment and their prognosis." (PMID 35158748, 2022). "Laryngeal cancer samples with high recurrence risk exhibited higher infiltration levels of T cells CD4 memory resting, NK cells, macrophage M0 in comparison to those with low recurrence risk." (PMID 34976784, 2021). "The percentage of CD4+ T cells as well as different CD4+ T cell subsets in TDLNs of laryngeal carcinoma were compared with those in TDLNs of tongue SCC." (PMID 36376825, 2022). "The expressions of CD4+HLA-DR+ markers were higher for pT3 and pT4 tumors, compared with pT2 laryngeal carcinomas." (PMID 36569825, 2022). "Hypopharyngeal carcinoma had less Tcm cells, Tfh cells, TGF-β response, and CD4 + T memory resting cells, but more wound healing than laryngeal carcinoma." (PMID 33173143, 2020). "Here, we showed that hypopharyngeal cancer had less T central memory cells, T follicular helper cells, TGF-beta response, and CD4 + T memory resting cells, but a higher wound healing score than laryngeal cancer." (PMID 33173143, 2020). "Hypopharyngeal cancer patients had less T central memory (Tcm) cells, T follicular helper (Tfh) cells, TGF-beta response, and CD4 + T memory resting cells, but a higher wound healing score than laryngeal cancer patients (p < 0.05)." (PMID 33173143, 2020). "The increased percentage of circulating CD4+ cells was found to predict response to induction chemotherapy in advanced laryngeal cancer." (PMID 31014274, 2019). "In addition, multiplex immunofluorescence was limited to only a few cell populations (CD8, M1-like macrophage, CD4, and Treg) due to insufficient tissue samples, particularly for patients with hypopharyngeal or laryngeal cancer." (PMID 38467604, 2024). "Our recently published study revealed that EBV infection may affect the PD-1/PD-L1 pathway and the development of laryngeal cancer; moreover, the level of PD-1 on CD4+ T cells in lymph nodes may serve as a marker for laryngeal cancer treatment and prognosis." (PMID 38256645, 2024). "In addition, more aggressive and deeply infiltrating laryngeal carcinomas were characterized by significantly higher values of the average expression of the HLA-DR marker on CD4+ T cells." (PMID 36569825, 2022). "Oxaliplatin-treated primary laryngeal cancer cell-pulsed DCs increased the IFN-γ-producing CD8+ T cells and suppressed CD4+CD25+FoxP3+ Tregs." (PMID 36131787, 2022). "Studies conducted by other researchers have also shown a reduced absolute number of CD3+, CD4+, and CD8+ T cells in patients with laryngeal cancer as compared to the control group." (PMID 35158748, 2022). "For example, CD4 and CD8 tumor-infiltrating lymphocytes show the potential to predict the prognosis of patients with recurrent laryngeal cancer." (PMID 34976784, 2021). "Pre-treatment biopsies from 80 oropharyngeal, 52 hypopharyngeal, and 29 laryngeal cancer patients were collected in a tissue microarray (TMA) and immunohistochemically stained for T-cell markers CD3, CD4, CD8, FoxP3, and PD1, and for immune checkpoint PD-L1." (PMID 31980916, 2020). "Certain markers were associated with tumor localization: CD57 higher density was seen in oropharyngeal tumors (p=0.0007), CD4 lower density was seen in laryngeal tumors (p=0.03) and lower CTLA4 tumor cell expression in laryngeal carcinomas (p=0.04)." (PMID 28038471, 2017).
laryngeal carcinoma (continued). "As for the study group, which included laryngeal cancer patients and their division into EBV+ and EBV- patients, statistical significance was observed only in the case of CD19+CD69+ B-lymphocytes in the blood, as well as CD4+PD-1." (PMID 38256645, 2024). "Finally, we evaluated the effects of DCs that were cocultured with oxaliplatin-treated primary laryngeal cancer cells on the populations of T cells, including IFN-γ-producing CD8+ T cells and CD4+CD25+FoxP3+ Treg cells." (PMID 36131787, 2022). "As for the second comparison, which was EBV+ laryngeal cancer patients and EBV-healthy volunteers, we observed no statistical significance only in the population of CD4+CD25+ lymphocytes in the blood." (PMID 38256645, 2024). "The positive correlation of the presence of EBV genetic material to the percentage of lymphocytes expressing PD-1 (i.e., CD4+ T lymphocytes in the blood and CD4+ and T CD8+ T cells in laryngeal cancer tissue and lymph nodes) may indicate a negative role for EBV in the process of anti-cancer defense." (PMID 35158748, 2022).
nematode infection (14 papers, 2009 to 2025). "To further explore the relative roles of RORα cell-intrinsic expression in CD4 cells or ILC2 in the expulsion of worms after nematode infection, we used CreERT2 mice for tamoxifen-inducible Rora deficiency in CD4 cells (Rorafl/flCD4CreERT2) and ILC2s (Rorafl/flID2CreERT2)." (PMID 37387671, 2023). "Collectively these data show that CD4+ T cell activation in the lymph nodes followed by entry to the pleural space are required for the expansion and M(IL-4) polarization of tissue-resident LCMs in nematode infection." (PMID 36948193, 2023). "However, emerging evidence suggests that ILC2–CD4+ T cell crosstalk in the context of a GI nematode infection is crucial for CD4+ T cell activation and function, as well as for worm clearance." (PMID 31072011, 2019). "In addition to ILC2s, S. venezuelensis infection induces strong Th2 differentiation of CD4+ helper T cells, as a general result of nematode infection." (PMID 30283458, 2018). "Trichinella and other nematode infection induce strong CD4+CD25+ regulatory T cell response characterized by high level of IL-10 and TGF-β, possibly through secreting some proteins with immunomodulatory function to suppress host immune response as a survival strategy." (PMID 28824599, 2017). "Having established that cholinergic signalling via the M3R contributed directly to CD4 Th2-driven immunity to nematode infection, we next tested whether this influenced immunity in a Th1 setting." (PMID 25629518, 2015). "It is interesting that there was no significant change in the level of IL-23 in the jejunum of infected mice, which indicated that the function of IL-23 in nematode infection is not as important as it does in intestine inflammation induced by IL-10 knockout or pathogenic CD4 T-cell transfer." (PMID 20016839, 2009). "Collectively, these data strongly suggest that Chi3l1 expression by both CD4 T cells and the CXCR5+ cDC2 cells promotes TH2 development following nematode infection." (PMID 41012147, 2025). "Hence, further work addressing the role of Th2/1 hybrid cells in the context of natural GI nematode infections is needed and the profiles of IL-4/IFN-γ expression by porcine Ascaris-specific CD4+ T cells are currently under investigation in our group." (PMID 35690651, 2022). "The CD4+ and CD8+ cell populations of EAE mice were affected by nematode infection." (PMID 28975357, 2018). "Using depletion experiments, we show that CD4+Foxp3+ regulatory T cells did not mediate the suppression of Ig response during chronic nematode infection." (PMID 25255463, 2014).
papilloma (14 papers, 2011 to 2023). A benign epithelial neoplasm that projects above the surrounding epithelial surface and consists of villous or arborescent outgrowths of fibrovascular stroma. "It is worth noting that increased an incidence of HPV-associated papillomas is observed in T-cell-immunosuppressed patients further emphasizing the role of CD4+ and/or CD8+ T-cell responses in PV-mediated disease." (PMID 29186900, 2017). "In the DMBA/TPA model, CB2-/- developed more and larger papillomas, had decreased spontaneous regression of papillomas, and displayed an altered systemic immune profile, including upregulated CD4+ T cells and dendritic cells, compared to WT mice." (PMID 37175480, 2023). "After switching to CD3+ T cell depletion, papillomas appeared upon 14/15 of mice that had been CD4+ T cell depleted throughout the challenge phase, 1/15 of CD8+ T cell depleted mice, and none in mice without any prior T cell depletion." (PMID 26495972, 2015). "Observational studies in humans have found that regression of anogenital warts is accompanied by a massive infiltration of CD4+ lymphocytes, both within the papilloma's stroma and the epithelium." (PMID 25121947, 2014). "At six weeks post-infection, the majority of the CD4-depleted SENCAR mice had developed papillomas (7/9; 78%)." (PMID 25121947, 2014). "The fact that removal of either subset allowed papilloma outgrowth suggests that cooperation between CD4+ and CD8+ T cells is required for effective control of infection and lesion development in SENCAR mice." (PMID 25121947, 2014). "CD4+ T cells from HPV-associated lesions showed impaired production of IL-1β, IL-18, IL2, IFN-γ, TNF-α, and the frequency of Ki-67+ CD4+ T cells was significantly reduced as compared to primary papillomas." (PMID 29257060, 2017). "However, upon challenge of female hairless SKH-1 mice, papillomas were observed in 3/20 mice despite normal presence of CD4+ and CD8+ T cells and the apparent immune-competence of this out-bred strain." (PMID 26495972, 2015). "CD4+ T cells were markedly reduced in wounds and papillomas of TNFR−/− BM chimeras." (PMID 25575023, 2015). "This correlated with recruitment of innate immune cells, including mast cells, granulocytes (both neutrophils and eosinophils) and adaptive immune cells, such as CD4+ T cells, which could potentially play a role in immuno-editing of nascent papillomas." (PMID 24843010, 2014). "However, combined CD4+8 depletion in the C57BL/6 mice did lead to MusPV1-induced papillomas (10/10)." (PMID 25121947, 2014). "At 6 weeks after virus inoculation, high levels of MusPV1 E1∧E4 spliced transcripts, as a measure of persistent infection, were found in infected skin tissues of CD3- and combined CD4+8-depleted animals, the two depletion conditions that resulted in papillomas." (PMID 25121947, 2014). "The FACS analysis showed that the Itga11−/− papillomas harbored significantly more macrophages and CD8+ T-cells and significantly fewer CD4+ T-cells and neutrophils than the Itga11+/+ papillomas." (PMID 36003785, 2022). "There were decreases in both infiltrating CD4 and CD8 T cells in the papillomas arising in K17KO blocked with anti-CXCR3, suggesting the increased infiltration of CD8+ T cells in K17KO mouse papillomas was mediated by the CXCL9/CXCL10/CXCR3 signaling axis." (PMID 31968015, 2020). "By contrast, combined depletion of CD4+ and CD8+ T cells was necessary for papilloma development in C57BL/6." (PMID 25121947, 2014). "When crude skin extracts taken from the mice 6 weeks after infection were evaluated by western blotting for the presence of L1 protein, it was only detected in the two groups that developed papillomas, CD3 depletion and the combined CD4+8 depletion." (PMID 25121947, 2014). "In BALB/c or C57BL/6 mice, neither CD4 + nor CD8 + T-cell removal alone was sufficient to form visible papillomas." (PMID 37127618, 2023).
papilloma (continued). "We found increased CD8+ T cells in K17KO papillomas, while differences in levels of other immune cells including CD4+ T cells were not significant." (PMID 31968015, 2020). "Genetically modified strains selectively deficient for B-cells or subpopulations of T-cells (CD4+, CD8+, or CD40+) did not develop MmuPV1-associated papillomas." (PMID 29186900, 2017). "Neither CD4+ nor CD8+ T cell depletion alone in BALB/c or C57BL/6 mice was sufficient to permit visible papilloma formation." (PMID 26495972, 2015). "The levels of MusPV1 genomic DNA detected in tail swabs of either CD4+ or CD8+ T cell depleted mice were >104-fold lower than for nude mice with papilloma, and were not significantly different from non-depleted mice." (PMID 26495972, 2015). "On the other hand, the mice with depletion of only CD4+ T cells (0/5) or of only CD8+ T cells (0/5) did not develop papillomas, which is in contrast to the results with the SENCAR mice under the same conditions." (PMID 25121947, 2014). "Therefore, the observation that loss of CD4+ T-cells in C57/BL6 and BALB/c was not sufficient to increase the susceptibility to MmuPV1-induced papillomas is somewhat surprising." (PMID 29186900, 2017). "We next determined whether depletion of either the CD4+ or the CD8+ T cell population alone, by administration of anti-CD4 or anti-CD8 mAbs, respectively, would be sufficient to induce sensitivity to MusPV1-induced papillomas in the SENCAR mice." (PMID 25121947, 2014). "At 6 weeks post-infection, we quantified infiltrating CD4+ and CD8+ T cells in the remaining papillomas that did not completely regress in K17KO control mice, papillomas in K17KO mice blocked with anti-CXCR3 and papillomas in untreated WT mice." (PMID 31968015, 2020). "Following 10 weeks of CD3+ T cell depletion, 14/15 of the initially CD4+ T cell depleted mice, but only 1/15 CD8+ T cell depleted mice and none of the initially mock-depleted mice grew papillomas." (PMID 26495972, 2015). "Therefore in C57BL/6 and BALB/c mice that were depleted of either CD4+ or CD8+ T cells and failed to develop papilloma post MusPV1 challenge, we tested for the presence of MusPV1 genomic DNA 5 weeks post-challenge via qPCR analysis of tail swabs." (PMID 26495972, 2015).
pneumococcal infection (14 papers, 2009 to 2025). Infections with bacteria of the species streptococcus pneumoniae. "Our findings indicate that key features of a pneumococcal-specific CD4+ T-cell immune response are altered at older age, which may contribute to enhanced susceptibility for pneumococcal infections." (PMID 35822055, 2021). "Altogether, this suggests that the reduced pneumococcal-specific CD4+ T-cell proliferation observed in young children as well as older adults could play a role in the increased susceptibility to pneumococcal infections in these age groups." (PMID 35822055, 2021). "Here, to our knowledge, for the first time evidence is presented for features of immunosenescence in CD4+ T cell responses to pneumococcal proteins that could contribute to susceptibility to pneumococcal infections at older age." (PMID 35822055, 2021). "The patient, in this case, developed pyopericardium despite being on ART with a CD4 count well beyond the threshold of pneumococcal infection." (PMID 40842968, 2025). "Taken together, these results demonstrate that lung BRM cells require CD4+ cells after recovery from pneumococcal infections." (PMID 38715601, 2024). "Pneumococcal protein-specific CD4+ T cells are considered key players in the control of pneumococcal infections." (PMID 35822055, 2021). "Although CD4+ Th17 responses are considered vital in providing protection against pneumococcal infections, the role of TRM is yet to be fully characterized." (PMID 30038624, 2018). "In terms of significance, a previous study indicated that IFN-γ production by CD4+ and CD8+ T cells in response to influenza virus infection enhanced susceptibility to secondary pneumococcal infection." (PMID 29621339, 2018). "In general, pneumococcal infection resulted in significantly higher HTL cytokine secretion by ex vivo PspA peptide-stimulated CD4+ T cells from the spleen as well as CLNs of S. pneumonia strain EF3030-challenged mice, than compared to naïve mice." (PMID 20195541, 2010). "CD4+ T cells were only one of many IFN-γ sources after pneumococcal infection." (PMID 35133985, 2022). "Many cellular sources of IFN-γ may decrease the reliance on CD4+ cells for AM remodeling after pneumococcal infection." (PMID 35133985, 2022). "Overall CD4+ TRM may play a role in the generation of naturally acquired immunity against pneumococcal infections, and should be considered in the development of heterotypic pneumococcal vaccines." (PMID 30038624, 2018). "These are the first data of which we are aware to describe the relation of nasal carriage of a pathogenic organism and lung IL-17A responses in humans and together support a role for effector IL-17A+ CD4+ memory T-cell responses in the defence of the lung against pneumococcal infection in adults." (PMID 23555269, 2013). "Our results are consistent with other reports where CD4 T cells were suggested to be poor predictors in the vaccine response to PPV23 and with reports that suggest loss of discrete memory B cell subsets leads to heightened susceptibility to pneumococcal infections." (PMID 25908996, 2015). "Pneumococcal-responding IL-17A-secreting CD4+ T-cells have not been described in the adult human lung and it is unknown whether they can be elicited by carriage and protect the lung from pneumococcal infection." (PMID 23555269, 2013). "In separate analyses, CD4+ and CD8+ cells were examined, and the number of CD4+ cells but not CD8+ cells producing IFN-γ was significantly higher on day 8 than day 1, immediately after the second pneumococcal infection." (PMID 35133985, 2022). "Neither adoptive transfer of splenic CD4+ T cells from infected mice into naïve recipients, nor inhibiting lung translocation of circulating CD4+ T cells with FTY720 in pathogen-experienced mice, had a significant effect on protection against pneumococcal infection challenge." (PMID 30038624, 2018).